EPCAM (epithelial cell adhesion molecule)
Diseases named in the same sentence as EPCAM in open-access papers (continued):
Sharing a sentence is not in itself a finding about the gene and the disease.
tumor (continued). "In contrast, the AdnaTest® uses an RT-PCR platform targeting three different transcripts (EpCAM, EGFR, CEA) to identify the tumor cells within the EpCAM-enriched cell fraction." (PMID 27182774, 2016). "Transcriptome analysis of samples that were enriched for tumor cells (EpCAM) revealed a significantly higher expression of PD-L1 mRNA in non-miliary compared to miliary (p=0.010)." (PMID 27665539, 2016). "Our results demonstrated that the EpCAM+ cell count in the peripheral blood of patients was significantly higher than that of controls, reflecting a tumor-bearing state, and thus indicating successful detection of CTCs using this method." (PMID 26897248, 2016). "Fluorescence microscopy demonstrated the distribution and tumour specificity of the anti-EpCAM agent." (PMID 27842504, 2016). "As target receptor we chose the human epithelial cell adhesion molecule (EpCAM), a putative marker of early tumor cells, and fused the EpCAM-specific DARPin Ac1 to the ectodomain of the G protein cytoplasmic tail variants." (PMID 27281338, 2016). "CTCs are rare events in the blood of patients and are believed to represent the epithelial population from a primary tumour of epithelial origin, thus EpCAM immunoisolation is considered an appropriate strategy." (PMID 27711186, 2016). "Enrichment of tumor cells can be achieved by a positive selection strategy using EpCAM antibody-coated magnetic beads before placing the effusion cells in culture." (PMID 27548442, 2016). "For that, we performed a flow cytometry assay with anti-EpCAM magnetic beads or antibody alone using SW480 tumour cells." (PMID 27711186, 2016). "Multivariate analysis showed that age (p=0.001, OR=1.619, 95%CI [1.204-2.178]) and tumor size (p=0.008, OR=1.492, 95%CI [1.109-2.008]) were independent related factors to EpCAM expression." (PMID 27557490, 2016). "In vivo, WM130 inhibited HCC xenograft growth, decreased the number of sphere-forming cells, and remarkably decreased the levels of EpCAM mRNA and protein in tumor xenografts." (PMID 27783993, 2016). "In human primary TNBC tissues, the reactivity of EpCAM(VU1D9) in tumor cells which have lost E‐cadherin or have undergone EMT was significantly lower than that in tumor cells which show E‐cadherin expression." (PMID 26775583, 2016). "Drug-target binding, NK cell related degranulation, and IFN-γ production was specific for both tumor related antigens in EpCAM and CD133 bearing cancer cell lines." (PMID 27650544, 2016). "Expression of cytokeratin among the selected cells, and the presence of cytokeratin+ aneuploid cells (>2N DNA content) among both CD90+ and EpCAM+ populations from all patients confirms the tumor origin of the cytokeratin+ and/or aneuploid subpopulations." (PMID 28721373, 2016). "In the IMS method small magnetic particles coated with the antibody MOC31 which recognizes the epithelial marker EpCAM, are used to isolate tumor cells from the lymph nodes, allowing fast screening of as much as 2 × 107 cells." (PMID 27316334, 2016). "A monoclonal antibody with medium high affinity for EpCAM, has been labelled with various radionuclides and has been extensively evaluated in several xenografted tumour models in mice." (PMID 27842504, 2016). "Next, based on our findings, the collection of circulating tumor cells should be used with caution to detect EPCAM-positive cells in patients with CRC because it can occasionally produce inaccurate results." (PMID 26528695, 2016). "We have shown, that factors presented in pr.CM increase both the ALDH positivity and expression of CD24−/CD44+/EpCAM+ cell surface markers in tumor cells." (PMID 26759169, 2016).
tumor (continued). "EpCAM is a biomarker of cancer stem cells, has the ability to reconstitute tumors, and is involved in tumor resistance to chemo/radiation therapy." (PMID 26984381, 2016). "The occurrence of EMT in tumor cells lead to downregulation of epithelial markers including EpCAM and reduces the sensitivity for detection of CTC50." (PMID 26916336, 2016). "While a significant correlation between EpCAM+CD147+ taMPs and CRC tumour volume was observed, a good correlation exceeding r = 0.5 between EpCAM+CD147+ taMPs and EpCAM+ taMPs with the commonly used UICC scores for CRC were not reached." (PMID 27127176, 2016). "One potential issue with using EpCAM to select CTCs or DTCs is that tumor cells are known to decrease this and other epithelial markers during the process of epithelial-to-mesenchymal transition." (PMID 27634877, 2016). "In this study, we assessed the frequency of EpCAM expression in both primary tumours and metastatic tissue of NSCLC patients." (PMID 27302574, 2016). "In this platform, tumor cells are first enriched immunomagnetically by EpCAM antibody-coupled magnetic beads." (PMID 27403030, 2016). "Expression of epithelial cell adhesion molecule, cytokeratins, tumour‐type‐specific biomarkers and CD45 was detected by immunofluorescence." (PMID 26178530, 2016). "In total, 78.7% of primary tumour tissue samples were EpCAM positive, with 40.4% showing intermediate and 38.3% evidencing strong EpCAM expression." (PMID 27302574, 2016). "A possible limitation of the strategies currently used for the enumeration of CTC from blood samples is the heterogeneous expression of EpCAM on tumor cells, especially on those undergoing EMT." (PMID 26961140, 2016). "Depending on the overall cut-off value 99 out of 103 investigated cancer patients disregarding their cancer entity were correctly as tumour bearer identified and 90 out of 95 were identified as cancers by EpCAM+CD147+ taMPs." (PMID 27127176, 2016). "This study shows the potential of an EpCAM specific NIR-fluorescent agent in combination with a clinically validated intraoperative imaging system to visualize various tumours during surgery." (PMID 27842504, 2016). "In our experiment, a ∼50-μm-thick tissue slice from a mouse pancreas tumour was incubated with biotinylated anti-mouse EpCAM antibody, followed by CN-PPV-BTE-streptavidin (CN-PPV-BTE-SA) Pdots." (PMID 27118210, 2016). "Levels of EpCAM+ tumor cells, CD45+ immune cells, CD45+/CD14+ MO/MA, and CD45+CD14+/CD16+ differentiated MO/MA were quantified by automated cell image analyses and compared between samples from miliary (n=6) and non-miliary (n=13) ascites." (PMID 27665539, 2016). "Levels of the same 26 lymphocyte populations as above were analyzed in digested and EpCAM+ cell depleted tumor tissues of ovarian (n=12) and peritoneal (n=15) origin from 20 HGSC patients." (PMID 27665539, 2016). "To date, in HCC, miR-130b has been shown to promote CD133+ CSC tumorigenicity and self-renewal, whereas miR-181 inhibition reduces the number of EpCAM+ CSCs and tumor-initiating ability." (PMID 27835990, 2016). "The STEMCELL and Miltenyi EpCAM positive selection kits were designed to purify cancer cells from human tissues and cell cultures, as well as to isolate circulating tumor cells from peripheral blood, stool samples and gastric aspirates." (PMID 27611664, 2016). "In another pilot study, CTCs were captured using CTC-Chip (anti-EpCAM) and detected in 42% of PCa patients before surgical tumor removal." (PMID 27479125, 2016). "CSCs can be identified (but not distinguished from nonmalignant stem cells) by their expression of various “stemness” markers including epithelial cell adhesion molecule (EpCAM), Oct-4, Nanog, and Notch and their presence within the tumor tissue compartment." (PMID 27366184, 2016). "The role of EMT in generating CTCs at the primary tumor site has been suggested, so it would seem reasonable to explain the heterogeneity of EpCAM expression." (PMID 27013581, 2016).
tumor (continued). "The potential of EpCAM targeting has recently been re-discovered, as tumour specific imaging was demonstrated for SPECT imaging." (PMID 27842504, 2016). "For GC, the presence of CTC and tumor markers (e.g. EpCAM/CK8/CK18/C19) seems prognostically the most relevant." (PMID 25862542, 2016). "Catumaxomab selectively lyses tumor cells by acting as a bridge for CD3-expressing T-cells, EpCAM-expressing tumor cells, and Fc receptor-expressing accessory cells, such as dendritic cells, macrophages, and NK cells." (PMID 26841833, 2016). "Among patients diagnosed as carcinoma, we therefore compared tumor cell detection by cytology (the reference method) to EpCAM+ MPs enumeration by flow cytometry, for their capacity of to differentiate benign and MPE." (PMID 26689993, 2016). "During this EMT, in addition to acquiring a migratory and invasive phenotype, tumor cells express mesenchymal proteins and concomitantly lose epithelial markers including the expression of EpCAM." (PMID 27501846, 2016). "IHC revealed a high percentage of tumor cells that expressed nestin and EpCAM in all of the tumor samples." (PMID 27414409, 2016). "The earliest method used to find CTCs was based on the detection of tumor cell surface specific markers such as EpCAM, cytokeratins (CKs) and glial fibrillary acidic protein (GFAP) etc.." (PMID 27517490, 2016). "Applying this approach to clinical samples, tumor cell populations were enriched using EpCAM targeted capture and compared to EMT targeted capture." (PMID 27049831, 2016). "TCGA-A tumours showed higher expression of most group I/FTEC epithelial proteins such as KRT7, MSLN, CDH6, ASS1 and EPCAM, while TCGA-B tumours had higher expression of the group III/IOSE mesenchymal proteins ITGA5, HMOX1, SMTN and GJA1 (refs 7, 34)." (PMID 27561551, 2016). "In this study we used CellSearch®, an EpCAM-based platform utilized for capturing of epithelial tumor cells from peripheral blood of mCRPC patients." (PMID 26975354, 2016). "As a novel EpCAM specific optical agent can be used in a wide variety of tumours, together with the knowledge from previous clinical trials and the results from this study, this paves the way for a fast and cost effective clinical translation." (PMID 27842504, 2016). "The CTC isolation process in this study was based on human EpCAM in a murine organism, eliminating the problem of non-tumor-derived EpCAM+ cells diluting the results." (PMID 27029058, 2016). "Blocking with anti-EpCAM combined with anti-CD133 scFv led to the highest level of blocking since both tumor related antigens are targeted by the TetraKE." (PMID 27650544, 2016). "At the same time, the expression of the epithelial cell adhesion molecule E-Cadherin is reduced, apparently allowing tumor cells to detach from the tumor mass during stromal infiltration." (PMID 27120783, 2016). "In this work, we first characterised a panel of cell lines representative of tumour heterogeneity, confirming the existence of tumour cell subpopulations with restricted epithelial features and supporting the limitations of EpCAM-based technologies." (PMID 27711186, 2016). "EpCAM was found significantly related to large tumor size and poor survival outcomes through IHC, which was similar to a previous study." (PMID 27557490, 2016). "Reported tumor-suppressive effects of forced KLF4 expression include the induction of the epithelial cell-adhesion molecule E-Cadherin and the cell cycle inhibitors p21Cip1 and p27Kip1 via direct binding of KLF4 to the respective promoter elements." (PMID 27323810, 2016). "Most current methods of circulating tumour cell (CTC) enrichment target the epithelial protein EpCAM, which is commonly expressed in adenocarcinoma cells." (PMID 27432216, 2016). "The expression of EpCAM was detected in 98 of 131 tumor categories and this rate varies from 59% (oral cavity) to 100% (pharynx) in HNSCC64." (PMID 26831813, 2016).
tumor (continued). "We demonstrate proof-in-concept data identifying expression of SSX2 in EpCAM positive circulating tumor cells from patients with advanced PC." (PMID 27769045, 2016). "EpCAM+ taMPs decreased at 7 days after curative R0 tumour resection suggesting a close dependence with tumour presence." (PMID 27127176, 2016). "In some experiments, the capabilities of cell proliferation and tumor formation in nude mice of GC cell lines were impaired after EpCAM downregulation." (PMID 27557490, 2016). "EpCAM is the epithelial cell surface marker used for the isolation of tumour cells that exhibit epithelial characteristics." (PMID 27118210, 2016). "The highest proportion of CD24+/CD44+/EpCAM+/CD133+ cells was detected in the cell line derived from the tumor of a patient with the shortest survival." (PMID 27414409, 2016). "For epithelial cancer types, antigen-dependent isolation devices rely mostly on the expression of cell surface Epithelial Cell Adhesion Molecule (EpCAM) to isolate CTCs, given its high expression in most of the tumor cells of epithelial origin." (PMID 27457474, 2016). "Involvement in prognostically relevant factors like enhanced tumor proliferation, resistance to chemo- and radiotherapy, reduced overall-survival, and selective expression on epithelial cells, make EpCAM a valuable marker for cancer targeting." (PMID 27650544, 2016). "The EpCAM directed antibody in this study has been extensively evaluated for imaging of various tumour models using radionuclides Technetium, Zirconium, Iodium and Rhenium." (PMID 27842504, 2016). "Having found that PBLs expressing EpCAM-specific CARs can kill PC3M tumor cells in vitro and in vivo, we next aimed to determine if adoptively transferring PBLs expressing EpCAM-specific CARs can target CSCs." (PMID 25636521, 2015). "Tumor initiating cells from liver metastases were characterised using combinations of EPCAM, Aldehyde dehydrogenase activity, CD133 and CD26." (PMID 25658706, 2015). "Well-characterized cell lines were selected to demonstrate the limitations of anti-EpCAM capture for isolation of tumor cells bearing different expression levels of EpCAM." (PMID 26267323, 2015). "Upon treating the MCF7 xenograft model which expresses higher levels of EpCAM, we were able to elucidate for the first time the tumor regression with our novel EpApt-siEp construct." (PMID 26176230, 2015). "Anti-EpCAM antibodies were used to label tumor cells to be counted by flow cytometry and human recombinant IgG1 anti-EpCAM monoclonal antibody (mAb) MT201 combined with propidium iodide (PI) for exclusion of dead cells." (PMID 26474755, 2015). "Nevertheless, emerging evidence has revealed highly dynamic localization and expression of EpCAM on tumor cells." (PMID 26718583, 2015). "The addition of solitomab to cultures of EpCAM expressing CS and autologous TAL appears to activate these tumor-anergic T cells in pleural fluid causing a cytotoxic T-cell response strong enough to eliminate resistant CS cells." (PMID 26474755, 2015). "EpCAM expression has been detected in certain tumor initiation cells (TICs), suggesting EpCAM as a possible target for enrichment of TICs and circulating tumor cells (CTCs)." (PMID 26317650, 2015). "We have recently summarized the EpCAM expression rates in most human tumour entities and we have shown that the expression in metastases usually reflects that of the primary tumour tissue." (PMID 26296970, 2015). "A high pre-operative level of EpCAM-positive circulating tumour cells and some gene expression signatures have also been found to be a predictor for recurrence." (PMID 25830231, 2015). "Catumaxomab is a trifunctional antibody binding to EpCAM on epithelial-like tumor cells and CD3+ T cells and can activate with its Fc part monocytes and NK cells." (PMID 25947366, 2015). "For this purpose, we used PC3 as the tumor model, of which only a small population of cells express EpCAM." (PMID 25636521, 2015).
tumor (continued). "Cytotoxicity was evaluated after co-culturing for 7 days EpCAM-positive CS tumor cells with solitomab and autologous TALs in a freshly collected pleural exudate fluid sample (APL13)." (PMID 26474755, 2015). "To date, Catumaxomab (Removab®) a trifunctional anti-EpCAM-anti-CD3 antibody is already used as second line therapy for malignant ascites in several tumor entities but with severe side effects." (PMID 25991672, 2015). "The antineoplastic effects of the anti-EpCAM antibody require the immune response; mAbs directed against EpCAM typically inhibit tumor growth via anti-idiotype networks, including both B and T cells, ADCC, and CDC death." (PMID 26317650, 2015). "Diverse clinical outcomes were found to correlate with quantity of EpCAM expressed on the tumor cells among different types of cancer." (PMID 26718583, 2015). "This potential is supported by the results that detection of CTCs by InCTC correlated with metastasis in the tumor models and InCTC detected more invasive CTCs than EpCAM-based selection method." (PMID 26247814, 2015). "More recently, the dynamic expression of EpCAM has been discussed in the context of tumor progression and in the process of embryonic stem-cell differentiation." (PMID 25477371, 2015). "As EpCAM is overexpressed in many cancers, our study also paves a way for the application of the potential anti-tumor agent in future clinical studies for other cancers." (PMID 26176230, 2015). "The detection rate was markedly higher than that obtained using the CellSearch system in a blinded manner, suggesting the superior sensitivity of our system in detecting EpCAM− tumor cells." (PMID 26107884, 2015). "Fluxion Biosciences has lately introduced a commercially available microfluidic technology (IsoFlux ®) with magnetic isolation zones to isolate EpCAM-positive tumor cells from biological samples." (PMID 25398926, 2015). "Consistent with the tumor cell killing, PBLs expressing EpCAM-specific CARs proliferated when co-cultured with PC3M cells, which suggests that the CAR-expressing PBLs can be activated by PC3M cells." (PMID 25636521, 2015). "Tumor cells displayed mature features, as most of the tumor cells were CD49flow/EpCAM+, CD271-/EpCAM+, and EpCAMhigh/Jam-Ahigh." (PMID 26311223, 2015). "So far, the exact mechanism of action of EpCAM contributing to the malignant potential of tumor cells is not fully understood, and therefore further exploration is needed." (PMID 26687301, 2015). "Overexpression of EPCAM is a phenotypical characteristic inherited since the tumour cell was in the lobular duct and remained present during the epithelial-mesenchymal transition (EMT) process." (PMID 25978366, 2015). "In 2009 the European Commission approved the first anti-EpCAM antibody named catumaxomab for the treatment of malignant ascites in cancer patients with EpCAM-positive tumours." (PMID 26296970, 2015). "CD45neg EpCAM+ primary tumor cells in all five independent samples tested express moderate to high level αFR on cell surface." (PMID 26101914, 2015). "Among the primary cell lines, 4 out of 5 (80 %) were found to express EpCAM in 100 % of the tumor cells." (PMID 26474755, 2015). "We fabricated an EpCAM targeting aptamer-siRNA chimera and investigated its anti-tumor property and EpCAM intracellular domain (EpICD) mediated signaling in epithelial cancer." (PMID 26176230, 2015). "During this process, tumor cells lose expression of specific epithelial markers including E-cadherin, EpCAM, and cytokeratin, and gain expression of mesenchymal cytoskeletal and adhesion proteins such as vimentin and N-cadherin." (PMID 26497689, 2015). "This approach was validated using cells from tumor cell lines with different sizes and EpCAM densities." (PMID 26184843, 2015). "Paradoxically, despite the broad expression of EpCAM in different tumour tissues, most EpCAM-based targeting strategies has shown only limited efficacy." (PMID 26296970, 2015).